MYC (MYC proto-oncogene, bHLH transcription factor)
Diseases named in the same sentence as MYC in open-access papers (continued):
Sharing a sentence is not in itself a finding about the gene and the disease.
breast cancer (continued). "ChIP-seq analysis reveals significant overlap between PML-, ER-, and Myc-bound promoters, suggesting their coordinated regulation of target gene expression, including genes involved in breast cancer stem cells (BCSCs), such as JAG1, KLF4, YAP1, SNAI1, and MYC." (PMID 37720048, 2023). "All of the genetic events examined were found to be co-occurring with MYC amplification in human breast cancer, especially supporting the use of the MMTV-Myc mouse model in studying MYC-driven human breast cancers." (PMID 37805590, 2023). "Scavenging mROS using MitoTEMPO similarly rescued MYC levels following IACS-010759 treatment in several cancer cell lines from ovarian, colorectal, and breast cancer." (PMID 37130865, 2023). "Our results demonstrated that in breast cancer, high AIMP2 expression was predominantly found in MTORC1 signaling, MYC TARGETS_V2, UNFOLDED_ PROTEIN_RESPONSE, and other signaling pathways." (PMID 38235352, 2023). "In breast cancers, ERLIN1 was discovered to be targeted by estrogen/MYC/miR-26 axis and promote cell growth." (PMID 38268722, 2023). "Breast cancers with c-MYC knockdown contain more CD3+ and CD8+ T cells, and c-MYC impairs T cell infiltration in vivo, leading to the formation of a “non-inflammatory tumor” microenvironment that induces immune evasion." (PMID 36721232, 2023). "Combined with above, c-MYC can promote angiogenesis by affecting TME components such as VEGF and TSP-1 in breast cancer." (PMID 36721232, 2023). "Via analysis of transcriptome data of breast cancer, FBXW9 was related to the activities of several cell cycle regulators including MYC and ESR1." (PMID 36982338, 2023). "MYC was reported to directly bind to and regulate the IRE1 promoter and enhancer regions in a breast cancer model." (PMID 36632215, 2023). "Taken together, this work demonstrates that MYC is upregulated by the crosstalk between ER and HER2 in AI-resistant breast cancer cells and that MYC-mediated glutamine metabolism is associated with AI resistance of breast cancer." (PMID 37258523, 2023). "For example, aloe emodin downregulates hTERT transcription in three breast cancer cell lines by upregulating E2F1 expression and downregulating c-MYC expression." (PMID 37612721, 2023). "In breast cancers, MYBL2 can transactivate the MYC and CCNB1 genes by binding their promoters and expediting the cell cycle of cancer cells." (PMID 36814821, 2023). "Both miR526b and miR655 enhanced CSC phenotypes in both luminal A and HER2 positive breast cancer, and MYC expression in MCF7-miR655 cells is marginally upregulated; however, MYC is a predicted target of miR655." (PMID 37128318, 2023). "Mechanistically, epinephrine activates LDHA to produce lactate, and the pH adjustment promotes USP28-dependent deubiquitination and stabilization of MYC, which in turn activates genes (such as SLUG) involved in breast cancer stem-like properties." (PMID 37444501, 2023). "In breast cancer cell lines, the promoters of PVT1 and MYC compete for the binding of intragenic enhancers that are located within the gene body of PVT1." (PMID 36901971, 2023). "Consistent with the findings in breast cancer that PVT1 promoter and enhancers engage in MYC regulation, our group recently reported that in PCa MYC-Pro distally interacts with PVT1 locus enhancers." (PMID 37828515, 2023).
breast cancer (continued). "In pancreatic and breast cancer cells, PP2A activation by KD of SET or by the SET antagonist OP449 decreases Ser62 and Thr58 phosphorylation of MYC and directs MYC towards ubiquitin-mediated proteasomal degradation." (PMID 37891368, 2023). "We also observed coincident binding throughout the TAD of transcription factors relevant to breast cancer, including CTCF, FOXA1, ESRRA (a relative of the estrogen receptor ER), and MYC." (PMID 37541849, 2023). "UNC0642 is a G9a catalytic inhibitor and across breast cancer cell lines, the anti-proliferative response to UNC0642 correlates with MYC sensitivity and gene signatures." (PMID 37781575, 2023). "In breast cancer cells, TCF12 stimulates the activation of c-MYC/Cyclin D1 pathway to accelerate cancer growth via facilitate CXCL12 of CAFs." (PMID 36721232, 2023). "MYC amplification and overexpression are well described in TNBC and basal-like subtypes of breast cancer, known as the deadliest subtypes of breast cancer currently, which must be accounted for in survival analysis." (PMID 37805590, 2023). "In external validation datasets, these associations, including deletions in PTEN and LRP1B or amplifications of MYC, CEP89 and ETV6, featured most prominently in the largest cohort of breast cancer samples." (PMID 37221612, 2023). "VEGF raised the expression level of c-MYC by activating STAT3 and enhances the self-renewal of breast cancer stem cells." (PMID 36721232, 2023). "KLF8 regulated mRNA and protein levels of CSCs markers, including OCT4, SOX2, MYC and NANOG in breast cancer cells." (PMID 37152043, 2023). "Notably, DEFFI revealed that higher signal intensity of PA also strongly correlated with areas of high MYC expression in primary human breast cancer biopsies supporting the clinical significance and the general validity of our observed connection between MYC and PA metabolism." (PMID 37946084, 2023). "For instance, in breast carcinoma USP22 and USP36 are known to regulate the cellular turnover of c-MYC." (PMID 36985413, 2023). "The in vivo potential of MYCMI-7 was investigated in three MYC-driven mouse tumor models: AML, breast cancer, and MYCN-amplified neuroblastoma." (PMID 36874405, 2022). "SETDB1 also enhances the protein expression of c-MYC and CCND1 to promote breast cancer cell cycle progression." (PMID 35372573, 2022). "The study also indicated that YTHDF2 was crucial to the survival of TNBC cells, while it is dispensable for cells that were less dependent on high expression levels of MYC, suggesting the elusive role of YTHDF2 in breast cancer." (PMID 35382893, 2022). "We also found EGFR, MYCN, and MYC in brain cancers;39,40BCL2, MYC, and the loci of IGH translocations in lymph-nodes cancer;41–43CDK12 in breast cancer; CCND1 in liver cancer; and RUNX1, GATA6, and PDE4D in esophageal cancer." (PMID 36163358, 2022). "Despite ZNF148 being an established node of the MYC-network in ES cells, and the significance of MYC in driving cancer stem cells traits, the role of ZNF148 in breast cancer remains elusive." (PMID 36207293, 2022). "Such interaction between YAP1/TAZ/TEAD-bound enhancers with promoters via chromatin looping has been reported in the MYC and TOP2A genes in an epithelial human breast cancer cell line." (PMID 35619099, 2022). "As expected, lysosomal gene mRNA levels were positively correlated with TFEB and TFE3 levels and negatively correlated with MYC and TET2 levels in breast cancer patients (normal-like tumors, n = 639)." (PMID 35351824, 2022).
breast cancer (continued). "Herein, we provide evidence for a direct transcriptional circuitry that functionally incorporates MYC, ZNF148, and ID1/3, regulating cancer stem cell traits in breast cancer." (PMID 36207293, 2022). "The ZNF148 depletion increased the MYC transcript level in MCF10A-GFP cells, consistent with the inverse expression correlation found in breast cancer patients." (PMID 36207293, 2022). "Besides, breast cancer 1 (BRCA1)-deficient cells were sensitized to the BET inhibitor, which reversed the MYC/TXNIP axis by inhibiting the activity of thioredoxin and elevating cellular oxidative stress, causing DNA damage that led to the death of BRCA1-deficient breast cancer cells." (PMID 35547739, 2022). "While this has not been observed for FTL yet, it has been reported, that co-targeting of BRD4 and RAC1 disrupts the MYC/G9a axis and enhances the expression of FTH1 in breast cancer cells." (PMID 36231049, 2022). "SUZ12 and EZH2 occupancy, along with E-box motifs and MYC occupancy, and H3K27me3 marks at the regulatory region of the ZNF148 locus provide a possible mechanism for MYC-induced repression of ZNF148 in breast cancer." (PMID 36207293, 2022). "A similar observation was reported in breast cancer, where transcriptional upregulation of several spliceosome components, including SRSF1, resulted in MYC hyperactivation and oncogenic translation impacting critical SF networks." (PMID 36535935, 2022). "AI-resistant breast cancer cells show significant upregulation of the glutamine transporters SLC1A5 and GLS, and inhibition of MYC, SLC1A5, and GLS decrease cell proliferation in AI-resistant cells." (PMID 36059650, 2022). "Another recently identified small compound, MYCMI-6, also inhibits c-MYC-MAX heterodimerisation by binding to the bHLH-LZ domain of c-MYC and abolishing c-MYC-mediated transcription in breast cancer cells." (PMID 35267559, 2022). "In HER2-positive breast cancer cells, AR promotes the expression of the HER3 gene, and the HER2/HER3 heterodimer activates the PI3K/AKT pathway and the MYC gene and promotes cell proliferation." (PMID 35207749, 2022). "MYC also represses lineage-specific transcription factors in mammary tissues, such as GATA3 and ESR1 to drive cancer stem cell-like states in breast cancer." (PMID 36207293, 2022). "In this study, we uncover a novel role of ZNF148 in suppressing TNBC cell growth and metastasis and provide evidence for a direct regulatory circuitry between MYC, ZNF148, and ID1/3 that impacts stem cell traits in breast cancer." (PMID 36207293, 2022). "When assessing enrichment pathways in the MDM2/MYC amplification group by GSEA within grade III ER+HER2− breast cancer, we identified that grade III ER+HER2− patients with MDM2/MYC amplification were enriched in cell cycle KEGG pathway." (PMID 34146382, 2022). "Among these stemness-related genes, the top 3 genes positively correlated with NOLC1 were MYC, ALDH18A1, and SMAD2 in breast cancer when analyzed using the TIMER2.0 database." (PMID 35174077, 2022). "In line with our observations in WB1P and WB1P-Myc mammary tumors, expression of CCL5 and pSTAT1 was induced upon BRCA1/2 depletion, and was suppressed in MYC-overexpressing BT-549 cells." (PMID 36323660, 2022). "SNIP1-TET2 interaction enhances the ability of TET2 to trans-activate c-MYC target genes, ultimately promoting anchorage-independent cell growth and cisplatin resistance of MCF-7 breast cancer cells." (PMID 35449131, 2022). "Further analyses using the GEPIA2 and TIMER2.0 databases revealed that NOLC1 was positively correlated with stemness-related genes, including MYC, ALDH18A1, ALDH1A1, SMAD2, SMAD3, etc., in both all breast cancer and TNBC." (PMID 35174077, 2022).
breast cancer (continued). "In neuroblastoma and breast cancer, tTG expression is reactivated by HDACi, which prevent HDAC1 recruitment by MYC." (PMID 33801599, 2021). "MYC (and HIF1A) has previously been found to be highly expressed in human breast cancer cells treated with Poly I:C." (PMID 34681079, 2021). "Expected staining patterns were demonstrated in control human tissues: seminoma for OCT4, normal skin for SOX2, seminoma for NANOG, breast cancer for KLF4 and normal prostatic tissue for c-MYC." (PMID 34685477, 2021). "To evaluate the relationship between CLDN6/TAZ/c–MYC expression and clinicopathological parameters, we did a TMA–IHC analysis of breast cancer patients." (PMID 35008557, 2021). "The results showed that in breast cancer, the expression of CREPT was positively correlated with Bcl-XL and weakly correlated with c-MYC and CCND1 at the mRNA level." (PMID 33531691, 2021). "We observed a high frequency (>50%) of copy number gain at three well-known breast cancer loci that contain potential oncogenes (chr8p11.23 [ZNF703] n = 8, 53.3%; chr8q24.2 [MYC] n = 9, 60%; chr19q12 [CCNE1] n = 9, 60%)." (PMID 34535742, 2021). "CPT1A is upregulated in MYC-overexpressing triple-negative breast cancer (TNBC), radiation-resistant breast cancer cells and radiation-derived breast cancer stem cells." (PMID 33858374, 2021). "H&N cancer had the highest frequencies of LRP1B (31.6%), and breast cancer had the highest frequency of PIK3CA and MYC (32.2% and 28.7%, respectively)." (PMID 34204917, 2021). "In breast cancer, NSUN2 is a MYC target gene, which is closely related to cell growth and proliferation." (PMID 33928086, 2021). "To explore the role of ACTL6A/MYC/CDK2 in the progression of TNBC, we detected these genes in breast cancer tissues and cell lines." (PMID 33541412, 2021). "We found that the MYC ChIP-seq signal is enriched at the CPSF1 promoter, in both keratinocytes as well as the breast cancer cell line MCF7." (PMID 33469008, 2021). "In breast cancer cell lines, ERα drives cell proliferation by activating expression of proliferative genes, including CCND1, MYC, E2Fs and FOXM1." (PMID 34831189, 2021). "We next examined the effect of TA on the phosphorylation of STAT3 and S6K1 in the MCF10A human mammary epithelial cell line overexpressing MYC and the MDA-MB-468 breast cancer line." (PMID 35095503, 2021). "Our study showed that levels of WNT/β‐CATENIN target genes CYCLIN D1, c‐MYC and SURVIVIN are elevated in breast cancer cells." (PMID 33462997, 2021). "We initially focused on transcription factors with reported links to breast cancer, and found that 16 transcription factors including HIF-1α, MYC, FOXP3, and E2F1 were predicted to target the JFK locus." (PMID 34336836, 2021). "In luminal breast cancer, ELF5 inhibits the transcription of ER, FOXA1, EGFR, MYC, and other proliferation-related genes, resulting in the suppression of estrogen sensitivity." (PMID 33742100, 2021). "We identified a group of TFs that showed L1-derived binding almost exclusively in MCF7 breast cancer cells, including ESR1, CTCF and MYC." (PMID 34070697, 2021). "In this review, we examine the role of crosstalk between PRLR and ERBB1/2 signaling pathways in the activation of unliganded ERα, cyclin-D1 and other oncogenic factors (MYC, FOS, JUN) in breast cancer." (PMID 34572912, 2021). "Positive staining was demonstrated on sections of control human tissues: tonsil for CD44, seminoma for OCT4 and NANOG, skin epidermis for SOX2, breast carcinoma for KLF4, and colon mucosa for c-MYC." (PMID 34685477, 2021). "Performing the same Outlier analyses, MYC and PIK3CA are overexpressed in 1 breast cancer data set each." (PMID 33176745, 2020).
breast cancer (continued). "Next, we compared the BRF2 Outlier results to known breast cancer biomarkers, HER2 (ERBB2), MYC, PIK3CA, and ER (ESR1) using the same stringent threshold criterion." (PMID 33176745, 2020). "Such MYC amplification-mediated molecular mechanism is specifically upregulated in the luminal B, HER2-positive, and TN breast cancers." (PMID 33489906, 2020). "Network analysis further reveals that Prunella vulgaris L. produces therapeutic effects on breast cancer by inhibiting key targets in the ErbB signaling pathway and estrogen signaling pathways, such as AKT1, EGFR, and MYC." (PMID 32978480, 2020). "We therefore investigated the role of MYC in bone marrow macrophages (BMM), polarized towards an M2 phenotype with IL-4 or with media conditioned by a breast cancer cell line." (PMID 32685002, 2020). "Frequently affected genes by CNVs in Chinese breast cancer patients were ERBB2 (25%), MIEN1 (25%), GRB7 (24%), TRPS1 (6%), MYC (6%), ERLIN2 (6%), PLPP5 (6%), NSD3 (6%), FGFR1 (6%), and CCND1 (5%)." (PMID 33173047, 2020). "cugWT1 is highly expressed in breast cancer cells, which can mediate tumor cell transformation and up-regulate c-MYC, BCL2, and EGFR expression; silencing it leads to decreased anchorage-independent growth and proliferation of breast cancer cells." (PMID 32210734, 2020). "Our current data showed that knocking out PRKD3 led to the reduction of p‐ERK1, p‐c‐MYC (Ser62), total c‐MYC and the down‐regulated expression of c‐MYC target genes in breast cancer cells." (PMID 31944568, 2020). "We also found that MYC expression correlates with CD47 expression in human whole breast tumor tissue, circulating monocytes, and tumor-associated monocytes in patients with breast cancer, indicating that MYC regulation of CD47 may be conserved within breast cancer TAMs as well." (PMID 32685002, 2020). "Pathway analysis also indicated that Prunella vulgaris L. exerts anti-breast cancer effects by inhibiting key targets in the estrogen pathway and ErbB pathways, such as AKT1, EGFR, and MYC." (PMID 32978480, 2020). "MST signaling decreases TEAD activity and expression of MYC oncogene in T-ALL cells and breast cancer cells as well as in xenograft mice model of breast cancer." (PMID 32375238, 2020). "The inhibition of ERK1 and c‐MYC phosphorylation further led to the lower protein level of c‐MYC and then reduced the expression of the c‐MYC target genes in breast cancer cells." (PMID 31944568, 2020). "In breast cancer cell lines, the inhibition of LIN28B suppresses MYC expression and increased miR-34a-5p levels expression, correlating with inhibition of glucose uptake/lactate production and a better patient’s prognosis." (PMID 32486505, 2020). "For example, using a transgenic model for MYC-driven mammary cancer (the WAP-Myc mouse model), we recently identified MYC-driven anti-apoptotic pathways as a vulnerability in MYC-high breast cancer." (PMID 33127915, 2020). "A few mouse models of breast cancer are driven by MYC, such as WAP-MYC and MMTV-MYC, but they are poorly metastatic." (PMID 33127915, 2020). "It was shown that besides p38, MKK3 can bind to multiple other proteins, including several drivers of breast cancer, such as CDK4, AURKA, FGFR4, EPHA2, and MYC." (PMID 32873298, 2020). "Altogether, our results provide a feasible explanation for the functional similarities of MYC, PIM1, and PML in TNBC and encourage further study of PML targeting strategies for the treatment of this breast cancer subtype." (PMID 31570853, 2020). "In contrast, the IL-1β/IL-1R1/β-catenin signaling pathway that regulates c-MYC, cyclin D1 (CCDN1), SNAIL1, and matrix metallopeptidases (MMP) 2 expression promotes proliferation, migration, and invasion in breast cancer." (PMID 32397236, 2020).